IRF1 (interferon regulatory factor 1)
Diseases named in the same sentence as IRF1 in open-access papers (continued):
Sharing a sentence is not in itself a finding about the gene and the disease.
breast carcinoma (continued). "For example, the ability of IFNγ-induced IRF1 to participate in several antitumor mechanisms has been demonstrated in breast cancer cells." (PMID 38396830, 2024). "For MLKL gene expression, IFNγ upregulates MLKL mRNA in breast carcinoma and cervical carcinoma cells, and IRF1 or STAT1 knockout reverses IFNγ-mediated induction of the MLKL mRNA level." (PMID 38671928, 2024). "Tumour infiltrating lymphocyte counts, PD‐L1 positivity and expression of the interferon regulatory genes IRF1, 4, 7 are synergistically downregulated in breast cancer metastases with a lower predictive profile for immunotherapy response." (PMID 38130025, 2024). "IRF1 has been shown to function as an antitumor agent in the following cancers: colorectal, pancreatic, hepatocellular, cervical, and breast cancer." (PMID 38789431, 2024). "It has been established that IRF1 works as a tumor suppressor in various tumor, including gastric cancer, esophageal cancer, breast cancer, and renal cell carcinoma." (PMID 36952469, 2023). "In this regard, a previous study on breast cancer reported that IFNγ, through its downstream effector IRF1, is capable of inducing the global AS perturbation of genes involved in the regulation of growth and differentiation, as well as cytokine genes." (PMID 38067106, 2023). "Studies have indicated that deletion or dysfunction of IRF-1 can induce tumor occurrence or progression in various cancers, including gastric cancer, breast cancer and hepatocellular carcinoma." (PMID 35092496, 2022). "PUMA was reported to mediate the mitochondrial apoptotic pathway in IRF-1-induced apoptosis in gastric and breast cancer cells." (PMID 34194609, 2021). "Specifically, BCA2 activates IRF1 in ER+ breast cell lines while it inhibits this transcription factor in ER– breast cancer cells." (PMID 34589482, 2021). "In sum, BCA2 is able to block NF-κB and activate IRF1 in ER+ breast cancer cell lines, but exhibits opposite effects on these molecules in other cell types." (PMID 34589482, 2021). "In 1104 breast cancer tissues (StarBase database), the positive correlation between IRF1 and IFI6 mRNA levels was supported by Spearman correlation analysis." (PMID 34399768, 2021). "RARRES3 has been shown to interact with the immunoproteasome and upregulate IRF1 in breast cancer cells, and to stimulate the proliferation of keratinocytes." (PMID 34349764, 2021). "IRF1 mainly functions as a tumor suppressor protein, low-expressing in several human cancers including breast cancer, endometrial carcinoma, leukemia, hepatocellular carcinoma and cholangiocarcinoma." (PMID 31113461, 2019). "The establishment of a tumor-suppressing role for IRF-1 in breast cancer and leukemia laid the foundations for further investigations exploring its function in other cancers." (PMID 29599126, 2018). "With respect to breast cancer, IRF-1 has been identified as an effector that restores the sensitivity of estrogen receptor-positive metastatic breast carcinoma to the anti-estrogenic drug fulvestrant." (PMID 29599126, 2018). "Loss of heterozygosity (LOH) at the IRF-1 locus was found in 32% of cases, providing evidence of a tumor-suppressive effect of IRF-1 in breast cancer." (PMID 29599126, 2018). "The identification of this polymorphism highlights the need for more thorough investigation of genetic changes in IRF-1 in patients with breast carcinoma and other tumors." (PMID 29599126, 2018). "IRF1 expression is lost in endocrine resistant breast cancer cell lines, and introduction of IRF1 sensitizes the cells to endocrine therapy and apoptosis." (PMID 26460486, 2015). "Expression of IRF1 or induction of IRF1 by IFN-γ in breast cancer cell lines suppresses proliferation, induces apoptosis and inhibits xenograft tumor formation of breast cancer cell lines." (PMID 26460486, 2015). "IRF1 expression is reduced in high-grade breast cancer while it is expressed in normal breast tissue." (PMID 26460486, 2015).
breast carcinoma (continued). "We also report extensive changes in transcriptional and AS regulation of cytokines in breast cancer epithelial cells in response to IRF-1 treatment." (PMID 24650050, 2014). "Others have shown that STAT1 and IRF1 are aberrantly expressed in some ER+ breast cancer tissues and cell lines and both have tumor suppressor properties." (PMID 24475282, 2014). "ChIP-chip analysis of IRF1 targets in IFN-gamma treated breast cancer cells identified a number of new targets in the DNA damage response including BRIP1." (PMID 25893139, 2013). "IRF-1 regulates ATP-dependent RNA helicase (BRIP1), a component of the Fanconi anemia/BRCA DNA repair pathway and a newly identified breast cancer susceptibility gene." (PMID 23420765, 2013). "In order to identify new IRF1 gene targets genome-wide we performed a ChIP-sequencing study in human breast cancer cells, H3396." (PMID 25893139, 2013). "Caspase activity assays are used to determine the overexpression of wild-type IRF-1 or dominant negative IRF-1 in breast cancer cells." (PMID 23420765, 2013). "Expression of IRF1 is downregulated in endocrine-resistant breast cancer cells, protecting these cells from IRF1-induced inhibition of proliferation and/or induction of cell death." (PMID 22295238, 2011). "Analyses of two publically available ONCOMINE cancer gene microarray datasets also imply an important tumor suppressive role for IRF1 in many sporadic breast cancers." (PMID 22295238, 2011). "MCF7 and T47D breast cancer cells expressing a dominant negative IRF1 (dnIRF1), which lacks the carboxyl-terminal transcriptional activation domain, do not undergo FAS-induced cell death and are, in turn, less sensitive to AEs." (PMID 22295238, 2011). "Overexpression of IRF1 in breast cancer cells can induce apoptosis, which is consistent with its tumor suppressive activity." (PMID 22295238, 2011). "This loss of heterozygosity is associated with an increased risk of recurrence and risk of death in the cases studied, strongly implicating a tumor suppressive role for the IRF1 gene in breast cancer." (PMID 22295238, 2011). "AE sensitivity is restored in AE-resistant breast cancer cells through an IRF1-dependent increase in mitochondrial outer membrane permeability and activation of the intrinsic apoptotic pathway." (PMID 22295238, 2011). "EGFR induces expression of IRF1, and IRF1 also can regulate EGFR expression, suggesting a possible role of IRF1 in EGFR overexpressing breast cancers." (PMID 22295238, 2011). "IRF1-A4396G is more frequent in human breast cancer cell lines than in the general population and is more frequently expressed in African American than Caucasian women." (PMID 22295238, 2011). "Most DCIS breast cancers retained expression of IRF1 in tumor tissue with 23 out of 24 staining positive, whereas IRF5 expression was significantly reduced with only 9 out of 24 staining positive." (PMID 22053985, 2011). "The experiments characterize STAT1/IRF1 as a key growth inhibitory and tumor suppressive signaling pathway that prevents mammary cancer formation by maintaining growth control." (PMID 22185785, 2011). "Overexpression of IRF1 induced apoptosis and inhibited tumor growth in mouse and human mammary cancer cells." (PMID 22053985, 2011). "We therefore investigated the possible role of RNASET2 with IRF1 in breast cancer." (PMID 40862725, 2025). "We studied the effect of resveratrol, genistein, apigenin and thymoquinone at non- toxic concentrations on the expression activation of type I IFN signaling genes (IFN-responsive genes IFI27 and OASL, and IFN regulatory factor IRF1) in another cell line, T47D (human breast cancer cells)." (PMID 39796235, 2025). "Additionally, IRF1 has been found to decrease the expression of the CXCL9 chemokine gene in breast cancer, leading to inhibition of the antitumor immune response." (PMID 40025540, 2025). "For example, IRF1-inactivating phosphorylation has been demonstrated in breast cancer cells." (PMID 38396830, 2024).
breast carcinoma (continued). "This dual role of IRF1 is context-dependent, particularly for the modulation of epithelial–mesenchymal plasticity, which may be of interest for future breast cancer treatment." (PMID 36936167, 2023). "The impact of RelA silencing on B2M was statistically significant, but the absolute difference was limited, which is consistent with the notion that other transcription factors, such as IRF1, facilitate the upregulation of B2M in ER+ breast cancer cells as in other cell types." (PMID 37450351, 2023). "In addition, IRF-1 mediates apoptosis in ovarian cancer and breast cancer and regulates autophagy in breast cancer cells, splenocytes and macrophages, which are cell fate determinants." (PMID 35092496, 2022). "For example, IRF1 could inhibit NFKB2 activity to induce breast cancer cell-specific growth inhibition." (PMID 34445498, 2021). "Additionally, IRF1 has been shown to have tumor suppressor functions in breast cancer through its inhibition of NF-kB36 and CASP8 activation and induction of apoptosis." (PMID 34234117, 2021). "IRF1 is an important factor mediating the response to anti-estrogens in ER+ breast cancer cells." (PMID 32843722, 2020). "Considering that IRF1 is an important transcription factor mediating apoptosis in breast cancer, we hypothesized that the induction of genes related to growth arrest and cell death by PAX2 could be partially attributed to IRF1 upregulation." (PMID 32843722, 2020). "Given the results that some of the PAX2 genes are regulated by IRF1 and the expression of IRF1 predicts survival in breast cancer patients, we examined whether PAX2 was able to induce apoptosis through IRF1 in MCF-7 cells." (PMID 32843722, 2020). "Notably, overexpression of IRF-1 in breast carcinoma cells has been found to result in a 15-fold down-regulation of survivin protein levels, which has been attributed to the suppression of cyclin B1, CDK-1, cyclin E, E2F1, CDK2, and CDK4 expression." (PMID 29599126, 2018). "Moreover, the results indicated that Dp significantly inhibits Akt activation and up-regulates IRF1 in a dose-dependent manner in breast cancer cells." (PMID 27388461, 2016). "Activities of ER, NF-kB and IRF1 determine antiestrogen sensitivity of ER+ breast cancer cells." (PMID 26460486, 2015). "Although IRF1 is associated with induction of apoptosis in breast cancer cell lines, expression of IRF1 in non-malignant murine cells did not cause apoptosis." (PMID 26460486, 2015). "Finally, numerous reports reveal low expression levels of IRF-1 mRNA in specific forms of cancer, including breast cancer and hepatocellular carinoma." (PMID 23420765, 2013). "We undertook a high-throughput study to identify IRF1 binding sites in breast cancer cells in order to comprehensively identify target pathways that may contribute to IRF1’s tumor suppressor activity." (PMID 25893139, 2013). "Moreover, enhanced IRF1 expression in breast cancer cells down-regulates the inhibitor of apoptosis protein, survivin (BIRC5)." (PMID 22295238, 2011). "IRF1 may play an important role in another breast cancer subgroup, the HER2-amplified breast cancers." (PMID 22295238, 2011). "IRF1 was used as a comparative control given its known expression and function in breast cancer." (PMID 22053985, 2011). "Initial evidence for this hypothesis was provided by the analysis of STAT1 and IRF1 protein expression in primary mouse mammary tumor tissue: the levels of IRF1 protein correlated with the expression levels of STAT1." (PMID 22185785, 2011). "Also in H3396 breast cancer cell lysates the pT/S antibody could immunoprecipitate endogenous human IRF1 induced by IFNγ treatment." (PMID 30854564, 2019). "Similarly, apoptosis induced by Tamoxifen in breast cancer cell lines is dependent on IRF1." (PMID 26460486, 2015).
breast carcinoma (continued). "Moreover, signaling pathways such as mitogen activated protein kinases (MAPK) and PI3K/Akt that are frequently activated in breast cancer cells modulate expression of IRF1 and STAT1, further impacting the levels of IFN-γ inducible CIITA and subsequent HLA-II expression on tumor cells." (PMID 24475282, 2014). "Thus, IRF-1 controls apoptosis through caspase-8 in breast cancer cells." (PMID 23420765, 2013). "Thus, miRNA-221/222 may serve to down-regulate the tumor suppressing effects of IRF1 in breast cancer cells following antiestrogen therapy." (PMID 22295238, 2011). "Thus, NPM1 may act by blocking/eliminating a caspase cascade in breast cancer cells through its ability to reduce IRF1 and signaling to apoptosis." (PMID 22295238, 2011). "The Janus kinase 1 (JAK1)/STAT1/IRF1 signaling pathway, which is activated by the binding of IFN-γ to IFN receptors, prevents mammary cancer formation by maintaining growth control." (PMID 41567365, 2026). "In this study, we identified expression patterns of IRF1, TMEM230, RNASET2, and syndecan 2 (SDC2) in different cell types of breast cancer patients using single-cell mRNA transcript analyses." (PMID 40862725, 2025). "MLKL expression is transcriptionally up-regulated by interferon-γ-regulatory factor 1 (IRF1) and the signal transducer and activator of transcription 1 (STAT1) in MDA-MB-231 breast cancer and HeLa cervical cancer cell lines." (PMID 38474369, 2024). "IRF1 is an IFN-inducible transcription factor and tumor suppressor that mediates ligand-independent apoptosis via caspase-8 activation in breast cancer cells." (PMID 38660315, 2024). "Collectively, our findings suggest that PARP7 inhibition induces IRF1- and IRF3-dependent apoptosis by promoting the degradation of FRA1 in FRA1-driven lung and breast cancer cell lines." (PMID 38011562, 2023). "In conclusion, our findings highlight how the PARP7-FRA1 axis regulates IRF1- and, consequently, IRF3-mediated cell intrinsic apoptosis signaling in lung and breast cancer cells." (PMID 38011562, 2023). "In breast cancer cells, IRF3 and MyD88 mRNAs were detected while IRF1 and IRF7 mRNAs were upregulated." (PMID 35737804, 2022). "Here, we demonstrate that UBR5 is required for IFN-γ-induced PD-L1 expression in breast cancer, and that transactivation of PDL1 gene expression by UBR5 is mediated through the PKR/STAT1/IRF1 pathway." (PMID 35836797, 2022). "The anticancer effects of Dp-3-G were due to suppression of Akt stimulation and enhanced IRF1 expression which are involved in controlling HOTAIR expression in carcinogen treated MCF10A, other breast cancer cells and in xenografted breast tumor." (PMID 35369062, 2022). "In this regard, the TFs IRF-1 and IRF-5 have been shown to act as tumor suppressors in breast cancer." (PMID 34367349, 2021). "Similar types of constitutive expression profiles of IRF1 and DTX3L mRNAs can be deduced from the RNA-seq results available for breast cancer tissues in the TCGA dataset." (PMID 32384653, 2020). "We evaluated the constitutive expression of IRF1/DTX3L mRNAs and proteins in 41 of our breast cancer cell-lines." (PMID 32384653, 2020). "Within the IFN genes, GBP1, CXCL10, IRF1, and STAT1 were described previously to be part of a tumor relapse-free signature in breast cancer patients." (PMID 30486871, 2018). "Silence of IRF1 expression via transfecting cells with IRF1 siRNAs significantly reduced the effects of Dp on HOTAIR, resulting in decreased cytotoxic effects of Dp on breast cancer cells." (PMID 27388461, 2016). "We undertook a high-throughput ChIP-sequencing study of IRF1 chromatin bound regions in unstimulated and IFN-gamma stimulated breast cancer cells in order to increase our understanding of pathways regulated by IRF1 in cells." (PMID 25893139, 2013).
breast carcinoma (continued). "By understanding the contribution of IRF1 to cellular growth and tumor suppression, we will further our knowledge on the signaling pathways of malignant diseases, which could lead to the development of novel and more effective therapeutic strategies for ER+ breast cancers." (PMID 22295238, 2011). "IRF1 and IRF5 expression were examined in FFPE specimens from patients with different stages of breast cancer by IF and IHC." (PMID 22053985, 2011). "It thus seems possible that STAT1 and IRF1 act in a common axis to suppress MIN and subsequently mammary tumor formation." (PMID 22185785, 2011). "In breast cancer, Lut upregulates C-X-C motif chemokine ligand 9/10 (CXCL9/10) transcription via signal transducer and activator of transcription 1-interferon regulatory factor 1 (STAT1-IRF1) activation, enhancing CD8+ T cell recruitment to the TME." (PMID 41479912, 2025). "In an organoid-based study of breast cancer, the use of adenovirus to block the interaction of HDAC3 with nuclear receptor co-repressor 2 (NCOR2) was found to up-regulate the expression of interferon regulatory factor 1 (IRF-1) and interferon-γ (IFN-γ) factors." (PMID 40006729, 2025). "Moreover, BCA2 regulates the tumor suppressor IRF1 independently of its SUMO E3 ligase activity, causing IRF1 activation in ER-positive and IRF1 downregulation in ER-negative breast cancers, which may explain the contradictory observations reported in relation to the role of BCA2 in breast cancer." (PMID 35887358, 2022). "Suppression of IRF1 expression by IRF1 siRNAs (TCanti-IRF1, stimulated HOTAIR expression and reduced the anticancer effects of Dp, signifying that Dp interferes with the regulation of Akt/IRF1/HOTAIR signaling pathway in breast cancer." (PMID 35369062, 2022). "Whereas up-regulation of BCA2 activates IRF1 in ER+ breast cancer cell lines, the opposite effect was observed for ER– and non-tumor breast cells." (PMID 34589482, 2021). "Interferon regulatory factor 1 (IRF-1) and IRF-2 expression in breast cancer tissue microarrays." (PMID 33537063, 2020). "Our findings that IRF1 expression contributes to the regulation of RARRES3, GBP4, and CTSS, but not to the regulation of TNFSF10, are further validated by mRNA expression data from breast cancer patients." (PMID 29192143, 2017). "Given the close relationship between IRF1 and EGFR family members, studies of the role of IRF1 in modifying responsiveness to taxanes and anthracyclines in the context of triple negative and Her2/neu breast cancers seem warranted." (PMID 22295238, 2011). "Moreover, according to CIDER the AP-1complex, together with the IRF1 TF, promotes the expression of RARA, linking theErbB pathway activation to the suppression of estrogen receptor activity, shown inthe more aggressive phenotypes of breast cancer." (PMID 26179713, 2015). "Immune infiltration scores suggest a positive correlation between IRF1 and immune infiltration in tumors like breast cancer, renal cancer, and cutaneous melanoma; however, no such correlation exists in AML, indicating that IRF1 may function uniquely in AML compared with other types of tumors." (PMID 40025540, 2025). "MLKL mRNA expression correlated with IRF1 and STAT1 mRNA expression, but not with ESR1 expression, in breast cancer cell lines." (PMID 38474369, 2024). "Our functional data indicated that IRF1 and DTX3L exert opposite effects on ATRA-dependent growth inhibition of breast cancer cells, suggesting that they are part of a negative feedback loop." (PMID 32384653, 2020). "Functional knockdown studies indicate that IRF1 and DTX3L are part of a negative feedback loop controlling ATRA-dependent growth inhibition of breast cancer cells." (PMID 32384653, 2020). "Interestingly, CXCL10, IRF1, and STAT1, shown to be expressed in breast cancers of patients who did not relapse, were also induced by EAD." (PMID 30486871, 2018).